ATR (ATR checkpoint kinase)
Diseases named in the same sentence as ATR in open-access papers (continued):
Sharing a sentence is not in itself a finding about the gene and the disease.
colorectal tumour (3 papers, 2022 to 2025). "Additionally, Sichuan University (2021) developed ATR inhibitors that exhibited significant anti-proliferative effects in LoVo cells and showed potent activity against colorectal tumours in animal models." (PMID 40256842, 2025). "The ATR, CHEK1 and CDC7 synthetic lethal effects can be replicated using small molecule inhibitors and in addition, the CDC7 dependency of colorectal tumour cell lines with reduced FBXW7 mRNA expression in the DepMap dataset was seen." (PMID 37866880, 2024).
endometrial tumor (3 papers, 2005 to 2024). "The CHEK1 mRNA expression level was elevated in both groups of endometrial tumors compared to KRAS and ATR mRNA expression levels." (PMID 38669256, 2024).
HIV-1 infection (3 papers, 2013 to 2023). The type species of lentivirus and the etiologic agent of acquired immunodeficiency syndrome (AIDS). "The results of our study showed that rs34660854 A and rs75368165 A in ATR gene were significantly associated with increased susceptibility to HIV-1 infection." (PMID 37468905, 2023). "It indicated that the rs34660854-A and rs75368165-A in ATR gene were the pathogenic factors for HIV-1 infection." (PMID 37468905, 2023). "Genotype analyses showed that under dominant and codominant models, the risk of HIV-1 infection was increased for ATR rs34660854 and rs75368165, Chk1 rs540436 and Cdc25C rs3756766, with OR values ranging from 1.337 to 1.460 (P < 0.05)." (PMID 37468905, 2023). "In this study, we aimed to genotype SNPs of ATR, Chk1, Cdc25C and CDK1 genes at G2/M checkpoint and analyze their associations with the susceptibility to HIV-1 infection and AIDS progression in a northern Chinese MSM population." (PMID 37468905, 2023). "In this study, 42 tSNPs in ATR, Chk1, Cdc25C and CDK1 gene were genotyped to analyze the association with susceptibility to HIV-1 infection and AIDS progress among MSM population in the northern China." (PMID 37468905, 2023). "A study also found that Vpr-induced structural alteration of DNA can trigger ATR-mediated DNA damage response and contributed to HIV-1 infection." (PMID 37468905, 2023). "Rs34660854 and rs37568165 in ATR gene, rs12576279 and rs540436 in Chk1 gene, rs3756766 in Cdc25C and rs139245206 in CDK1 gene were associated with susceptibility to HIV-1 infection." (PMID 37468905, 2023). "Therefore, GMDR software was used to investigate the impact of interaction between ATR, Chk1, Cdc25C and CDK1 gene polymorphisms on HIV-1 infection susceptibility." (PMID 37468905, 2023). "Combined with observations that Vpr activates ATM and ATR and that macrophages are resistant to DSBs compared with monocytes, our data suggest that the enhancement of IN-CA–independent viral transduction into MDMs may be a pivotal role of Vpr in HIV-1 infection." (PMID 23432899, 2013).
insulinoma (3 papers, 2017 to 2021). "The activation of ATR is not cell type selective, as nitric oxide stimulates Chk1 phosphorylation in both MEF and insulinoma cells." (PMID 33567339, 2021).
Intellectual disability (3 papers, 2021 to 2025). "The neurological symptoms of SS patients, such as seizure and intellectual disabilities, may reflect abnormal neuron activities and suggest a potential role for ATR in postmitotic neurons." (PMID 40105243, 2025).
lung squamous cell carcinoma (3 papers, 2015 to 2024). "A further common genetic alteration is ATR amplification that is found in about 10.1% of lung squamous-cell carcinoma, ~6.6% of esophageal cancer, ~5.7% of head and neck carcinomas and a minority of other cancer cases." (PMID 33224881, 2020). "ATR deep deletions are very rare and found in a minority of mesothelioma (~1.2%) and squamous-cell lung cancer (~0.4%)." (PMID 33224881, 2020). "However, the Lung-MAP SWOG S1400G trial (NCT02154490) found that talazoparib (Talzenna) had a lower ORR of 4% in patients with advanced refractory lung squamous cell carcinoma, specifically in tumors with BRCA1/2, ATM, ATR, and PALB2 mutations." (PMID 38989152, 2024). "ATR, ATRIP and TOPBP1 are altered in 45/212 lung squamous cell carcinomas (21 %) in the TCGA database." (PMID 26438152, 2015).
neuroendocrine carcinoma (3 papers, 2020 to 2025). A malignant neuroendocrine neoplasm composed of cells containing secretory granules that stain positive for NSE and chromogranin. "Further investigation would also be warranted whether neuroendocrine cancers where ribosome biogenesis is impaired would respond to combination treatment of IMPDH and ATR inhibitors which predominantly generates RS leading to cellular cytotoxicity as demonstrated in the present study." (PMID 40491496, 2025).
oral squamous cell carcinoma (3 papers, 2021 to 2025). "Another study found that the activity of natural killer (NK) cells was boosted by immune checkpoint blockade (targeting either PD-1 or T cell immunoreceptor with Ig and ITIM domains (TIGIT)) in combination with ATR inhibition and radiotherapy in a murine oral squamous cell carcinoma model." (PMID 37346039, 2023).
oropharyngeal cancer (3 papers, 2020 to 2023). Carcinoma, predominantly squamous cell, arising from the epithelial cells of the oropharynx. "The specifics of this transformation mechanism seems to diverge from that described by Tanaka and collaborators in the family with predisposition to oropharyngeal cancer since the identified missense variant did not cause a decrease in the expression of ATR and was associated with LOH in the tumor." (PMID 36749285, 2023).
ovarian tumor (3 papers, 2019 to 2021). "The first generation of ATR and CHK1 inhibitors has been shown to sensitize ovarian tumors to DNA-damaging agents that primarily induce replicative stress as their mechanism of action." (PMID 32316968, 2020). "However, by analyzing the gene data of GSE114206 dataset and TCGA database, it showed no statistically significant in correlation of CXCL2 and ATR/CHK1 expression in ovarian tumor." (PMID 34474677, 2021).
progeroid syndrome (3 papers, 2013 to 2015). A group of rare genetic disorders which mimic physiological aging, making affected individuals appear to be older than they are. "Further evidence that lamins are involved in regulating ATR comes from the finding that either the expression of LA mutants that cause progeria or the silencing of LA expression by shRNA, causes the ubiquitin mediated degradation of ATR." (PMID 23894423, 2013). "In addition, mice with a hypomorphic mutation in the DNA damage response protein ATR develop a progeroid syndrome, and this phenotype is due to high levels of replicative stress and DNA damage during embryogenesis, but not in adult tissues." (PMID 25155611, 2014). "Fibroblasts derived from various progeroid syndromes have been shown to have a reduced replicative capacity compared to normal cells; such syndromes include WS, ATR-SS, AT and HGPS." (PMID 25214013, 2015).
retinoblastoma (3 papers, 2021 to 2023). A malignant tumor that originates in the nuclear layer of the retina. "Gene set enrichment analysis using TCGA‐LUAD dataset revealed that ‘Retinoblastoma Gene in Cancer’, ‘Cell Cycle’, ‘DNA IR‐damage and cellular response via ATR’, and ‘G1 to S cell cycle control’ were identified as enrichment pathways in high expression of MCM genes group." (PMID 37517032, 2023).
rhabdomyosarcoma (3 papers, 2022 to 2025). A rare aggressive malignant mesenchymal neoplasm arising from skeletal muscle. "To identify which of the known factors may influence rhabdomyosarcoma cells’ sensitivity to ATR inhibition, we assessed their presence in eleven rhabdomyosarcoma cell lines and their association with ATR inhibitor sensitivity." (PMID 35879366, 2022). "Expression of PAX3-FOXO1 in muscle progenitor cells is not only sufficient to increase sensitivity to ATR inhibition, but PAX3-FOXO1-expressing rhabdomyosarcoma cells also exhibit increased sensitivity to structurally diverse inhibitors of ATR." (PMID 35879366, 2022). "Untransformed mouse myoblast cells engineered to express PAX3-FOXO1, as well as PAX3-FOXO1-expressing rhabdomyosarcoma cell lines, accumulated unrepaired DNA damage and underwent apoptosis upon treatment with selective inhibitors of ATR signaling." (PMID 35879366, 2022). "Here the authors show preclinical evidence for ATR inhibitors as a therapeutic option for alveolar rhabdomyosarcoma." (PMID 35879366, 2022). "Based on our results in human cell line models, we next sought to explore the effect of single agent ATR inhibition and its combination with olaparib in mice harboring patient-derived rhabdomyosarcoma xenografts (PDX)." (PMID 35879366, 2022). "The inhibition of ATR induces apoptosis in alveolar rhabdomyosarcoma." (PMID 39941729, 2025). "Consistently, BRCA1 knock down also sensitized rhabdomyosarcoma cells to ATR inhibition." (PMID 35879366, 2022). "Notably, CHK1, a downstream target of ATR, is inhibited by prexasertib, which is currently being clinically investigated in combination with chemotherapy for patients with relapsed rhabdomyosarcoma (NCT04095221)." (PMID 35879366, 2022). "We hypothesized that due to its effect on BRCA1 phosphorylation and HR activity, pharmacological ATR inhibition could sensitize rhabdomyosarcoma cells to PARP1 inhibition." (PMID 35879366, 2022). "Our findings warrant the future investigation of ATR inhibitors in clinical trials, such as the currently undergoing phase I/II trial of BAY 1895344 (Elimusertib) in relapsed PAX3-FOXO1-expressing rhabdomyosarcoma (NCT05071209)." (PMID 35879366, 2022).
skin cutaneous melanoma (3 papers, 2019 to 2024). "Therefore, we tested whether ATR inhibition by berzosertib would enhance the cytotoxic effect of irradiated cutaneous melanoma cell lines." (PMID 39594759, 2024).
acute leukemia (2 papers, 2015 to 2017). A clonal (malignant) hematopoietic disorder with an acute onset, affecting the bone marrow and the peripheral blood. "We have previously shown that CX-5461 activates ATM/ATR pathway in acute leukemia, arrests cells in G2 phase and synergizes with ATR inhibitor in killing these cells." (PMID 26472108, 2015). "Collectively our results quantify the control exerted by ATR on convergent nucleotide biosynthetic routes, and provide the rationale to co-target both signaling (ATR) and metabolic (RNR and dCK) mechanisms in acute leukemia for optimal therapeutic efficacy." (PMID 28808226, 2017).
Adenovirus infection (2 papers, 2020 to 2025). "The replication of HSV DNA inactivates ATR/Chk1 signaling, which is like the ATR inactivation observed upon Adenovirus infection." (PMID 40284937, 2025). "Adenovirus infection blocks the ATM/ATR-mediated DDR through oncoprotein reorganization (E1b55K/E4orf6 and Edorf3) and degradation of the MRN complex." (PMID 32479542, 2020).
atherosclerosis (2 papers, 2015 to 2020). A disease characterized by the build-up of fatty material and calcium deposition in the arterial wall resulting in partial or complete occlusion of the arterial lumen. "ATR could act on the KDR gene, which is one of the key molecules related to angiogenesis and a strong risk factor for atherosclerosis, while CR can act on its ligand VEGFA." (PMID 32802132, 2020). "Furthermore, based on the T-P network analysis, ATR and CR treatment of AD mainly depends on the PI3K signaling pathway, MAPK signaling pathway, neuroactive ligand–receptor interaction, and fluid shear stress and atherosclerosis, which regulate the nervous and vascular systems." (PMID 32802132, 2020).
Autoimmunity (2 papers, 2022). The occurrence of an immune reaction against the organism's own cells or tissues. "Our study adds a new layer for ATR-mediated pathway in autoimmunity and, specifically, in regulating B cell responses in SLE." (PMID 36306362, 2022). "While relevant to understanding SLE pathogenesis and B cell–mediated autoimmune diseases, this may also provide novel insights into the specific regulatory role of ATR signaling in autoimmunity and into its coordination by IFN signaling." (PMID 36306362, 2022). "The role of the DDR in innate cells in this context remains unclear and it is tempting to hypothesize that ATR acts to limit systemic levels of type I IFN and autoimmunity." (PMID 35330617, 2022).
cardiac ischemia (2 papers, 2020 to 2023). "Then we investigated whether PNE enhanced cardiac miR-181a expression, altered cardiac ATR gene methylation, H19 lncRNA expression and cardiac ischemia-sensitive signaling proteins (such as ATR, TGF-β/Smads, and autophagy-related genes) in adult offspring." (PMID 33052248, 2020).
chronic myeloid leukemia (2 papers, 2017 to 2019). "The oncogenic BCR-ABL fusion protein disrupts ATR-dependent intra-S phase checkpoint in chronic myeloid leukemia after etoposide treatment, by causing DNA strand break formation." (PMID 28415748, 2017).
cognitive defects (2 papers, 2021). "Due to the essentiality of the Atr gene in vivo, the role of ATR in the pathogenesis of postnatal neurological and cognitive defects remains unknown." (PMID 34210973, 2021).
colorectal adenocarcinoma (2 papers, 2021 to 2024). The most common type of colorectal carcinoma. "AZ20 inhibits ATR and ATR-mediated phosphorylation of Chk1 in HT29 colorectal adenocarcinoma tumor cells." (PMID 38279263, 2024).
cyst (2 papers, 2017 to 2021). A sac-like closed membranous structure that may be empty or contain fluid or amorphous material. "First, inhibition of either ATM or ATR reduced cyst growth in vitro in the MDCK cyst model, but the latter was associated with a dysplastic cystic phenotype." (PMID 33802342, 2021). "In contrast, the ATR inhibitor, VE-821, reduced in vitro MDCK cyst growth but caused dysplastic changes." (PMID 33802342, 2021).
epilepsy (2 papers, 2015 to 2021). A brain disorder characterized by episodes of abnormally increased neuronal discharge resulting in transient episodes of sensory or motor neurological dysfunction, or psychic dysfunction. "The susceptibility of ATR-FBΔ mice to epilepsy strongly suggests that altered neuronal activity in mutant mice, which progresses during aging, renders neurons vulnerable to stress or environmental stimuli." (PMID 34210973, 2021). "Its deletion relieves the repression of SYT2 and PROT in promoting membrane fusion to facilitate fast neurotransmitter release, therein rendering ATR-FB∆ mice more susceptible to epilepsy." (PMID 34210973, 2021). "Genes implicated in primary microcephaly with associated features such as cognitive and motor impairment and epilepsy includeSLC25A19,ATR,ARFGEF2, andRAB3GAP119." (PMID 26535115, 2015).
fibrosarcoma (2 papers, 2021 to 2023). A malignant mesenchymal fibroblastic neoplasm affecting the soft tissue and bone. "For example, in fibrosarcoma and CHO cells, diminished STAT3 activity was associated with reduced ATR induction." (PMID 37126127, 2023).
gastric tumors (2 papers, 2021 to 2025).
herpesvirus infections (2 papers, 2015 to 2023). "The function of the other key DNA damage signaling regulator, ATR, is also modified during herpesvirus infections." (PMID 26714015, 2015). "This has been particularly evidenced in herpesvirus infections, for which ATM and ATR DNA damage pathway proteins play beneficial roles for viral replication." (PMID 36951571, 2023).
Huntington disease (2 papers, 2019 to 2020). Huntington disease (HD) is a rare neurodegenerative disorder of the central nervous system characterized by unwanted choreatic movements, behavioral and psychiatric disturbances and dementia. "They found that repetitive DNA relied most on ATR to avoid breaks—potentially implicating ATR in the many nervous system diseases that are associated with expanded microsatellite repeats, such as Huntington's disease, fragile X syndrome, frontotemporal dementia and amyotrophic lateral sclerosis." (PMID 33584810, 2020).
Hyperglycemia (2 papers, 2023 to 2025). An increased concentration of glucose in the blood.
Infertility (2 papers, 2013 to 2018). "ATM−/− mice show pleiotropic defects (growth retardation, infertility, immune defect and high incidence of T cell lymphomas), and ATR−/− mice show embryonic lethality." (PMID 24833228, 2013). "In mammals, knockout ATR mutation results in embryonic lethality, while an ATM mutation results in pleiotrobic defects (e.g., growth defects, neurologic dysfunction, and infertility)." (PMID 24833228, 2013). "Finally, our finding that in vivo exposure to AZ20 causes meiotic prophase arrest is relevant when considering the use of ATR inhibitors in cancer therapy, since meiotic arrest may result in infertility." (PMID 29977027, 2018).
kidney injury (2 papers, 2020 to 2024). Trauma to the kidney. "A very recent study has established that activation of proximal tubule ATR confers protective effects against the maladaptive DNA repair and consequent renal fibrosis induced by kidney injury." (PMID 31884071, 2020).
liver cancer (2 papers, 2021 to 2025). An epithelial or non-epithelial malignant neoplasm that arises from the liver. "Our data indicate that the levels of replication stress determine the sensitivity of liver cancer cells to ATR or CHK1 inhibitors." (PMID 34663432, 2021). "Western blot analysis of γH2AX, a marker for both DNA damage and DNA replication stress, indicated that the basal levels of γH2AX were clearly higher in four sensitive liver cancer cell lines compared to three cell lines resistant to ATR or CHK1 inhibitors." (PMID 34663432, 2021). "For liver cancer cells that are resistant to ATR or CHK1 inhibition, treatment with CDC7 inhibitors induces strong DNA replication stress and consequently such drugs show striking synergy with ATR or CHK1 inhibitors." (PMID 34663432, 2021). "We observed synergistic effects on cell proliferation by XL413 and ATR or CHK1 inhibition (AZD6738 or MK-8776) in all three ATR or CHK1 inhibitor resistant liver cancer cell lines." (PMID 34663432, 2021). "Here, we use integrated bioinformatics and functional genetics approaches to study the therapeutic options for the use of ATR or CHK1 inhibitors in liver cancer." (PMID 34663432, 2021). "In the field of liver cancer, despite some preliminary findings, the therapeutic roles of ATR or CHK1 inhibitors remain to be explored." (PMID 34663432, 2021). "Pharmacological inhibition of ATR or CHK1 leads to robust proliferation inhibition in liver cancer cells having a high basal level of replication stress." (PMID 34663432, 2021). "In liver cancer, however, despite some preliminary findings, the therapeutic benefit of ATR and CHK1 inhibitors remain to be explored." (PMID 34663432, 2021). "Functionally, liver cancer cell lines can be classified as either sensitive (Huh7, HepG2, MHCC97H, and SNU398) or resistant (Huh6, PLC/PRF/5, and SNU449) to ATR or CHK1 inhibitors." (PMID 34663432, 2021). "Similar to CDC7 inhibition, treatment with cisplatin synthesizes liver cancer cells to AZD6738, further supporting the relation between DNA replication stress and the sensitivity of ATR or CHK1 inhibitors." (PMID 34663432, 2021). "Next, we tested the potencies of ATR inhibitor AZD6738 and CHK1 inhibitor MK-8776 in liver cancer cell lines." (PMID 34663432, 2021). "Together, these findings suggest that ATR and CHK1 could represent potential therapeutic targets for liver cancer." (PMID 34663432, 2021).